CD4 (CD4 molecule)
Diseases named in the same sentence as CD4 in open-access papers (continued):
Sharing a sentence is not in itself a finding about the gene and the disease.
Immunodeficiency (continued). "Similarly, the significant immune dysfunction observed in HTLV-1-infected CD4+ T cells likely contributes to immunocompromise in individuals with HAM." (PMID 40004169, 2025). "Our findings suggest that exhausted T cells, especially for activated CD4+ T (e.g. CD4_Th1) and effector CD8 + T cells (e.g. CD8_Effector‐GZMK(+)), may have a key role in causing immune dysfunction in severe coinfected patients." (PMID 41163794, 2025). "GIMAP5 is essential for T cell survival and homeostasis; its deficiency leads to impaired maturation and survival of CD4+ and CD8+ T cells, as well as defective NK and NKT cell development, and is associated with immune dysfunction and liver pathology in both rodents and humans." (PMID 41042382, 2025). "Similarly, other immunological biomarkers were similar between the two groups, while IPEX patients showed increased memory CD4+ T cells, increased eosinophils, and immunoglobulin E (IgE) levels, as seen in other immunodeficiencies with immune dysregulation." (PMID 39475830, 2024). "This is evidenced by phenotype observations in patients or animal models with abnormal ORAI1 or STIM1 expression, which shows compromised CD4+ and CD8+ T cell functions related with humoral and cellular immunity, ultimately leading to immunodeficiencies and susceptibility to severe infections." (PMID 38791278, 2024). "This may allow arginase-expressing M2 macrophages to dampen the CD4+ T-cell effector response and may worsen immunodeficiency." (PMID 37966797, 2024). "Specifically, levels of total HIV-1 DNA appeared to be high among adolescents with immunodeficiency, more precisely in those with CD4 T cells <350 cell/mm3 as compared to those having CD4 T cells ≥350 cell/mm3 (median [IQR] log10 HIV-1 copies/mL: 2.88 [2.64–3.33] vs. 2.48 [2.23–2.94]); (p = 0.05)." (PMID 38601701, 2024). "Furthermore, immunodeficiency is associated with ART, secondary prophylaxis, and CD4 lymphocyte count." (PMID 39186781, 2024). "For example, the bone-marrow disease hyper-IgM immunodeficiency could arise from mutations in CD40 gene, affecting B cells, or mutations in CD40 ligand (CD40LG), affecting CD4 T cells." (PMID 38197427, 2024). "Less common immunodeficiencies are described as well with their respective CD4/CD8 ratios." (PMID 39728019, 2024). "Altogether, whereas the associations with viral load were more complex and not significant for NLRP3, our data support that HIV infection induces IFI16 in human monocytes, and both IFI16 and NLRP3 expression is higher in PWH with more pronounced immunodeficiency (i.e., with lower CD4 T cell counts)." (PMID 39000248, 2024). "Indeed, only CD4 T cells were predicted as likely affected by hyper-IgM immunodeficiency (PrEDiCT = 1.6, FDR <0.048)." (PMID 38197427, 2024). "Immune dysfunction was defined as a CD4+ count <500 cells/μl or a CD4+/CD8+ ratio <1." (PMID 39086487, 2024). "Previous studies have shown that MS is characterized by immune dysregulation, mainly driven by myelin-specific autoreactive CD4+T cells, and is closely related to immune dysfunction, transitional activation of immune cells, and an imbalance in the ratio of immune cell subpopulations." (PMID 39010157, 2024). "CD38+ B cells, exhibiting elevated levels of ZAP-70 and heightened protein tyrosine phosphorylation, are associated with increased production of pro-inflammatory cytokines and suppression of CD4+ T cell proliferation, thus contributing to the pathogenesis of immune disorders." (PMID 39044820, 2024). "Recent studies have shown that KDM7C regulates interleukin 4 production in CD4+ T cells and may play a role in the development of immune diseases and that it directly destabilises SREBP1c and reduces SREBP1c‐dependent lipogenesis." (PMID 39643939, 2024).
Immunodeficiency (continued). "Regarding indicators related to immune status, a greater proportion of individuals in the severe PTB group had immune dysfunction, especially a significantly higher percentage of individuals with a CD4+ T-cell count <500 cells/μl than did individuals in the general PTB group." (PMID 39086487, 2024). "This section focuses on their regulatory effects on CD4+T cells in immune diseases." (PMID 39758422, 2024). "Elevated levels of BTLA on CD4+ T cells will eventually result in CD8+ T-cell immune disorders." (PMID 38418488, 2024). "Proper functioning of the thymus is essential for correct immune system function, and prolonged CD4 expression under these conditions may result in immune disorders in the affected animals later in life." (PMID 39273192, 2024). "In this study, the recurrent patients have the lower CD4+/CD8+ ratio, indicating the immune deficiency in recurrent patients, which may also be one of the reasons for their recurrence." (PMID 37904699, 2023). "Although the mechanisms of this effect are unknown, some researchers suggested that the poor CD4 count contributed to a subtle immunodeficiency, while the increased number of potentially dysfunctional CD8 count could create a toxic inflammatory environment." (PMID 38131882, 2023). "Because a low ratio is indicative of immunodeficiency, a higher CD4/8 ratio is preferable." (PMID 37444491, 2023). "Hence, a lower CD4 count indicates substantial immunodeficiency and increased vulnerability to infection." (PMID 37885727, 2023). "As observed, the presence of other associated diseases in addition to coinfection can worsen the clinical situation of these patients, who are in advanced immunodeficiency, since at the beginning of treatment, 70.9% of the patients had a CD4 T lymphocyte count below 200 cells/mm3." (PMID 36980489, 2023). "Chronic inflammation, immunodeficiency/reduced CD4 counts, endothelial dysfunction, increased thrombosis and accelerated atherosclerosis are among the phenomena that have been associated with the occurrence of cardiovascular events in both PLWHIV and healthy individuals." (PMID 37110381, 2023). "Notably, the overall immune activities in male patients from age group 7 were lowered extensively compared to the females in CD4.T.prog, CD8.T.prog, and Mono.prog, suggesting remarkable immune deficiency in these aged male patients." (PMID 37750090, 2023). "Certain tests may be advised to know patients' health status like CD4 counts for the level of immunodeficiency." (PMID 37214076, 2023). "It was found that HIV infection could weaken the immune system, exacerbating immunodeficiency in a setting of immune activation in which CD4+ T lymphocytes depletion might be crucial, while CD8+ T-cells are abnormally activated and increased in number." (PMID 36845097, 2023). "The ratio of CD4 to CD8 can be used to judge the immune dysfunction." (PMID 37118659, 2023). "Moreover, 61.9% of patients with pulmonary infection had immune dysfunction, with a ratio of CD4+ to CD8+ T lymphocytes below two." (PMID 38098502, 2023). "CD4+ T cells regulate the inflammatory environment in RA through various subsets, CD4+/CD8+ is associated with immune dysfunction, an increased CD4+/CD8+ ratio has been implicated in patients with RA, while the development and suppressive activity of Treg cells require the master regulator FOXP3." (PMID 36615560, 2023). "Collectively, our data reveal that CCR4 blockade is effective in the overall recovery of various levels of immune dysfunction in HBsAg-specific T cells including both CD4 and CD8 T cells that might help in HBV clearance." (PMID 37081509, 2023). "Overall, insufficient IL-15 levels and decreased responsiveness of CD4+CD25+CD127dim/− Tregs to IL-15 signaling might contribute to the immune dysfunction in CHB patients with T2DM." (PMID 35801423, 2023).
Immunodeficiency (continued). "Abnormal CD4/CD8 ratio was associated with immune dysfunction in patients, the unstable CD4+ /CD8+ ratio was not conducive to the balance of cellular immune responses." (PMID 37759316, 2023). "This indicates the integral role of CD4 in immune disorders for both diseases." (PMID 38018597, 2023). "As current and nadir CD4+ T cell counts may act as different surrogates for persistent immune dysfunction, we assessed effects on the humoral repertoire through multivariate models with both parameters separately and with current CD4 adjusted by nadir CD4." (PMID 36805331, 2023). "The CD4/CD8 ratio has emerged as a useful indicator of immune dysfunction in PWH." (PMID 37639938, 2023). "HIV infects CD4 T cells and monocytes/macrophages of the immune system, and its impact on the number of T cells of various subtypes is part of the hallmark of initial HIV infection and, ultimately, its accompanying immunodeficiency." (PMID 35880029, 2022). "Moreover, a relatively lower CD4+/CD8+ T cell ratio was observed in the EMD subtype (p < 0.05), which usually indicates more advanced tumors or immune deficiency in cancer patients." (PMID 35600848, 2022). "In addition, the ratio of CD4+ to CD8+ is a sensitive indicator of human immunodeficiency, and the decrease of this ratio indicates that the body's immune function is inhibited." (PMID 36212973, 2022). "Moreover, DTG-based regimens still showed a more rapid increase in CD4+ T-cell count when the study population contained patients with severe immunodeficiency with CD4 ≤ 50 cells/μL." (PMID 36700216, 2022). "This study reported immunodeficiency as a CD4 count of less than 350 cells/mm3." (PMID 36483323, 2022). "Immunodeficiency reduces CD4 cells, which may lead to a greater burden of Cryptococcus in patients, and systemic inflammation may cause symptoms." (PMID 35383254, 2022). "Immunodeficiency, especially HIV, and low CD4 counts are acknowledged important risk factors." (PMID 35746750, 2022). "Thus, CMV and Cryptococcus infections are opportunistic conditions occurring during the period of severe immunodeficiency, commonly in patients with a CD4 count < 50 cells/mm3." (PMID 35042469, 2022). "Fourth, there was a lack of different ranges of CD4 T cell counts to evaluate the association with immunodeficiency and RCC." (PMID 35433425, 2022). "We next examined the T cell cytokine expression profile of vaccinated and unvaccinated mice during immunodeficiency by quantifying the number of effector cytokine-producing CD4+ T cells in CD8-depleted mice and the number of effector cytokine-producing CD8+ T cells in CD4-depleted mice." (PMID 36229573, 2022). "As such, vaccine formulations exhibiting high efficacy in animal models that resemble immunodeficiencies associated with cryptococcosis (e.g., lacking CD4+ T cells) are in high demand." (PMID 35615354, 2022). "In addition, PHSML has been reported to downregulate the indicators related to the proliferation and activation of CD4+ T cells, and induce uncontrollable inflammatory responses, resulting in organismal immune disorders." (PMID 35572554, 2022). "Although IL4-producing immune cells (e.g., basophils, mast cells, and Th2 cells) play a crucial role in Th2-mediated immune diseases such as atopic dermatitis (AD), DCs are also essential because they can initiate immune responses and modulate CD4+ T cell polarization." (PMID 36557876, 2022). "In our study, immune dysfunction in the model rats, including the downregulation of the CD4/CD8 ratio, decreased in CD4+CD25+FOXP3+ Tregs and the secretion of inflammatory factors TNF-α and IFN-γ increased, which reflected a negative regulation of haematopoiesis." (PMID 35434141, 2022). "This may be related to PHSML-induced CD4+ T cells immune dysfunction, resulting in TIPE2 losing normal immune regulatory function, and the related mechanism needs to be further studied." (PMID 35572554, 2022).
Immunodeficiency (continued). "The HIV-1 Vpr could be produced and released from HIV-1 sequestered tissue reservoirs during cART treatment, and Vpr has been shown to participate in the HIV-mediated immune dysfunction and CD4+ T-cell depletion." (PMID 35154126, 2022). "There are reports suggesting that CD4:CD8 ratio may better reflect immune dysfunction in well-controlled HIV infection than CD4+ cell count alone." (PMID 36298842, 2022). "Currently, routine state-of-the-art monitoring of the extent of immune deficiency caused by an HIV infection usually relies on surveillance of surrogate parameters, most commonly CD4+ cell count, but more comprehensive determination of immune status and prediction of IR are difficult." (PMID 33537915, 2021). "Published studies have shown that the CD4/CD8 ratio in the peripheral blood of healthy adults is approximately 2:1, and an altered ratio is indicative of diseases that are associated with the immunodeficiency or autoimmunity." (PMID 34282123, 2021). "Of interest, the low expression of CXCR4 as well as the class-A1 Rhodopsin-like receptors in COVID-derived CD4+ naïve T cells resulted in a reduced responsiveness of the IL-10 signaling pathway, which may contribute to immunodeficiency in patients." (PMID 34944610, 2021). "Under immunodeficiency conditions, in cHL there is a depletion of CD4+ T-cells and an increased infiltration of M1 macrophages, and hence, HIV may also contribute to this permissive microenvironment." (PMID 34771697, 2021). "The evidence of CD4+CXCL13+ T cells shaping TME composition may represent a LR-CHL–specific mechanism of immune dysfunction, suggesting that therapeutic targeting of these cells might reverse their immunosuppressive effects." (PMID 34615710, 2021). "The CD4+ T cell subset is closely related to the immune disorder of GD." (PMID 34926448, 2021). "Our current study shows that hPMSC-Exo carrying miR-21 could upregulate the expression of PTEN/PI3K-Nrf2 signaling pathway in senescent CD4+ T cells, improve the antioxidant capacity of CD4+ T cells, and alleviate age-related immune dysfunction." (PMID 34887868, 2021). "Although there seems to be an increased risk of clinical infections after RTX treatment, the rate of infection is poorly correlated with the types of immune diseases and is closely correlated with low hypogammaglobulinemia, neutropenia, CD4+ T cell dysfunction, etc.." (PMID 35116041, 2021). "Despite well-maintained pre-COVID CD4 counts and suppressed HIVVL, HIV-associated immune dysfunction may affect the person’s ability to respond to the exuberant inflammatory reaction, resulting in clinical deterioration from COVID-19." (PMID 34851963, 2021). "Identification of the pathways involved in this process will allow us to design strategies directed to block effector functions that CD4+CD28null T lymphocytes have in the target tissue, which may represent therapeutic approaches in this immune disorder." (PMID 34202487, 2021). "Therefore, HIV infection not only depletes activated CD4+ T cells but also alters the differentiation program of surviving CD4+ T cells, resulting in long-term immune dysfunction." (PMID 33430234, 2021). "Controlling CD4+ metabolic pathways can be important in fighting against some immune diseases." (PMID 33483502, 2021). "While the CD4-Cre+/TgMettl14FL/FL conditional knockout mice do not seem to develop any other pathology, this does not rule out a possible immune deficiency–like phenotype." (PMID 32634481, 2020). "These include a Lipoarabinomannan (LAM) antigen tests for TB and cryptococcosis (CrAg) antigen tests, which could be guided by immunodeficiency represented by CD4 cell count testing." (PMID 32589367, 2020). "However, we didn’t find such tendency, even though CD4 count less than 200/μL was used as a marker of severe immunodeficiency." (PMID 33032537, 2020).
Immunodeficiency (continued). "Nevertheless, it cannot be excluded that the poor CD4 recovery in the LR group could be the result of further too low baseline CD4 counts and further advance of immunodeficiency." (PMID 33240269, 2020). "Defining the pathogenesis of residual viremia, immune dysfunction and incomplete CD4 T-cell recovery may aid in recognizing possible cure or strategies to eliminate HIV from infected patients with controlled or residual viremia." (PMID 32941433, 2020). "This increased CD4+T subset may extend to inflammatory sites of target organs and may contribute to the immune disorders in SCD patients with osteonecrosis." (PMID 33132753, 2020). "Moreover, IL-21 is well known to be related to immune diseases and regulates the differentiation of CD4+ T-cells." (PMID 32684837, 2020). "Saliva α-diversity was associated with CD4/CD8 T cell ratio, a measure of immune dysfunction inversely correlated with morbidity and mortality (Shannon Padj = 0.08; Chao Padj = 0.03) and with activated CD8 T cells (percentage of HLA-DR+ CD38+ CD4 T cells, Chao Padj = 0.02)." (PMID 32024712, 2020). "Moreover, aVNS therapy improved PD-related immune disorders by altering the percentage of subsets of CD4+ T cells." (PMID 33568987, 2020). "As we know, antibody production by B cells requires help from CD4+T cells, so defects in CD4+T cells may lead to severe immunodeficiencies." (PMID 30994732, 2019). "Although there is a risk of immunodeficiency following the depletion of CD4+ T cells, current protocol did not completely and continuously deplete CD4+ helper T cells even at two injections of 1.0 mg/kg." (PMID 31340866, 2019). "More importantly, follow-up immunological investigations reveal that, despite previously highlighted phenotypic and immunological discrepancies among the here presented patients, all three of them display a progressive immunodeficiency with gradual depletion of B lymphocytes and CD4+ T cell counts." (PMID 30987377, 2019). "A state of immunodeficiency was excluded, based on normal CD4 count and patient’s clinical history." (PMID 30626344, 2019). "With a median duration of 4 years on ART, the severe immunodeficiency (CD4 < 200 cells/mm3) and the high viral load (HIV-RNA > 10.000 copies/ml), there is a late detection of treatment failure and a substantial accumulation of DRMs in about nine out of ten patients in routine care." (PMID 30871487, 2019). "Low CD4 T cell counts are not routinely reported as a marker of immune deficiency among HIV-negative individuals, as is the norm among their HIV positive counterparts." (PMID 31517248, 2019). "Since SCFA play a critical role in controlling Treg generation and maturation, we speculated that Blend 2 alleviated inflammation and immune dysfunction by promoting a SCFA-dependent maturation of CD4+ Foxp3+T cells." (PMID 30717413, 2019). "However, other small trials in patients with auto-immune disease are underpowered to show clinically significant changes in Tregs as a proportion of CD4 cells." (PMID 31550254, 2019). "Assessment of JAK/STAT5 signaling dynamics may therefore provide a sensitive cellular readout of immune dysfunction that reflects the integration of multiple signals ultimately driving abnormal CD4+T cell responses early in the pathogenesis of preeclampsia." (PMID 31263463, 2019). "However, immune dysfunctions such as chronic immune activation accompanied by low CD4+ T cell counts persist in a subset of patients receiving cART23." (PMID 30979916, 2019). "Although monkeys infected with this virus exhibited increased levels of chronic immune activation, the HIV-1-like SIVagm construct failed to cause accelerated CD4+ T cell depletion and immunodeficiency." (PMID 29636452, 2018). "The absolute numbers of patients with very low CD4 counts might, however, remain a sensitive barometer, where patients will often still be tested for advanced immunodeficiency for clinical reasons." (PMID 29514233, 2018).